EPCAM (epithelial cell adhesion molecule)
Diseases named in the same sentence as EPCAM in open-access papers (continued):
Sharing a sentence is not in itself a finding about the gene and the disease.
lung carcinoma (175 papers, 2006 to 2026). "For instance, EpCAM was recently found to be upregulated in primary lung cancer compared to normal lung tissues caused by gene amplification and promoter hypomethylation." (PMID 40258059, 2025). "Cigarette smoking, the major cause of lung cancer, also significantly contributes to the amplification of the EPCAM gene and its strong expression." (PMID 38791091, 2024). "Recently, we reported that the formation of CD45+EpCAM+ cells in patients with lung cancer is associated with tumor cell-derived exosomes." (PMID 36147748, 2022). "The underlying mechanisms accounting for dynamic expression of EpCAM in different stages of lung cancer were explored with respect to both genetic and epigenetic regulation manners." (PMID 36077658, 2022). "The sensitivity of the assay was high enough to detect tumour associated antigens, such as EpCAM from H3122 lung cancer-derived EVs, at a concentration of 3.125 × 106 EVs/μl in plasma." (PMID 35135541, 2022). "In the field of EPCAM, many studies indicate that it can act as a potential diagnostic and prognostic biomarker for different types of cancers, including lung cancer." (PMID 36428585, 2022). "Given that tumor microenvironment, in particular tumor-associated macrophage, is involved in EMT and metastasis in lung cancer, the effect of macrophage on tumor cell EpCAM expression was examined." (PMID 36077658, 2022). "In lung cancer, increased EpCAM expression along with Metastasis-associated protein 1 (MTA1) promoted migration." (PMID 34209658, 2021). "In renal clear cell carcinoma and thyroid carcinoma, EpCAM expression has been correlated with improved survival, and in lung cancer, EpCAM overexpression was also associated with improved or not worse prognosis." (PMID 23959111, 2014). "Moreover, a minority of patients with lung cancer (6.67%) harbors gene loss and promoter hypermethylation, but EpCAM upregulation, which is likely caused by smoking-induced ROS." (PMID 36077658, 2022). "Epithelial cell adhesion molecule (EpCAM), a carcinoma-associated antigen, is known to be overexpressed in a variety of human adenocarcinomas and squamous cell carcinomas, such as colon, stomach, prostate and lung cancers." (PMID 31489935, 2019). "EpCAM has been widely investigated for its diagnostic and therapeutic potential as it is expressed in the majority of human epithelial cancers, including breast, colon, gastric, head and neck, prostate, pancreas, ovarian and lung cancer." (PMID 25265904, 2014). "Our flow cytometry-based analysis that identifies increased expression of EpCAM in Stage I/II cancer-confirmed samples, as well as samples from high-risk participants who continue to smoke, suggests that EpCAM expression may be of specific importance in early lung cancer detection." (PMID 35976857, 2022). "In lung cancer patient samples, depletion of EpCAM+ exosomes significantly reduced RBC miR‐93‐5p, while spike‐in restored the signal (p < 0.05)." (PMID 41159542, 2026). "As an example, epithelial cell adhesion molecule (EpCAM) is expressed on the surface of epithelial cells, including tumor cells of breast or lung cancer origin." (PMID 40100294, 2025). "This method was successfully used in spike-in experiments comprising a series of lung cancer cell lines with different EpCAM expression levels." (PMID 40076201, 2025). "Some biomarkers, including carcinoembryonic antigen (CEA), epithelial cell adhesion molecule (EpCAM), circulating microRNAs (miRNAs), and circulating tumor DNA (ctDNA), can be used for lung cancer detection." (PMID 40277545, 2025). "In summary, EpCAM is a highly promising target for IMI in guided LN dissection in lung cancer surgeries." (PMID 41087662, 2025). "Recently, our work revealed that amplification of the EPCAM gene leads to its high expression in primary lung cancer." (PMID 38791091, 2024).
lung carcinoma (continued). "Despite these limitations, the cited studies demonstrated the potential of EpCAM-targeted radionuclide imaging in lung cancer and suggested that using smaller imaging probes is advantageous." (PMID 39199590, 2024). "For example, the epigenetic restoration of EpCAM expression in metastatic lung cancers by HDACi and/or DNMTi probably enhances the yield of CTC isolation and the specific killing of cancer cells by anti-EpCAM CAR-T therapy." (PMID 38791091, 2024). "A high level of EpCAM overexpression in lung cancer makes this protein a promising target for targeted therapy." (PMID 39199590, 2024). "Upon treatment with histone deacetylase inhibitors (HDACis), remarkable induction of EpCAM expression is detected in metastatic lung cancer cells." (PMID 38791091, 2024). "Studies have shown that cell surface vimentin (CSV) is more efficient than EpCAM in capturing CTCs in solid tumors, including lung cancer." (PMID 39085849, 2024). "For example, the protein methyltransferase G9a promotes cell invasion and metastasis through the cell adhesion molecule epithelial cell adhesion molecule (Ep‐CAM) in lung cancer." (PMID 37220590, 2023). "Promoter methylation was one of the mechanisms accounting for EpCAM repression in highly metastatic lung cancer cell A549, which was evidenced by strong restoration of EpCAM expression by DNMT inhibitor 5-aza-dC in both time- and dose-dependent manners." (PMID 36077658, 2022). "DNMT inhibitor 5-aza-dC, HDAC inhibitor MS-275, and TGFβ neutralizing antibody are able to restore EpCAM expression in highly metastatic lung cancer cells." (PMID 36077658, 2022). "In our study, we found a significantly higher rate of apoptotic cells in CD45+EpCAM+ versus CD45+EpCAM− cells from solid tumors of patients with lung cancer." (PMID 35711455, 2022). "The prototypical EMT inducer TGFβ and its downstream signaling molecule SNAI2 were inversely correlated with EpCAM expression in human lung cancers." (PMID 36077658, 2022). "The method, easily adaptable to any laboratory, has been validated using plasma from lung cancer patients in which the epithelial cell marker EpCAM has been detected on EVs." (PMID 35135541, 2022). "In this regard, an important achievement in lung cancer has recently been reached through the study of CD44+/EPCAM+ cell populations, which showed a high correlation and affinity with CSCs, previously identified by ALDH high cells." (PMID 35205721, 2022). "Statistical analysis of ROC/AUC for serum biomarkers' level and CD45+EpCAM+ cell ratio in PBMCs of healthy volunteers and lung cancer patients." (PMID 36147748, 2022). "We confirmed the presence of CD45+EpCAM+ cells in lung cancer, and these cells exhibited higher apoptosis than CD45+EpCAM− cells." (PMID 35711455, 2022). "Co-culture of exosomes derived from HCC827 human lung cancer cells with PBMCs resulted in the formation of CD45+EpCAM+ cells." (PMID 35711455, 2022). "CD45+EpCAM+ cells were detected in the tumor tissues of all 38 patients with lung cancer, and an increased CD45+EpCAM+ cell ratio was present in PBMCs of 28 patients (73.7%) of these patients." (PMID 36147748, 2022). "In summary, we demonstrated that CD45+EpCAM+ cell formation and increased apoptosis occur in patients with primary lung cancer and from PBMCs treated with HCC827 cell-derived exosomes." (PMID 35711455, 2022). "This was also the first study that explored the possibility of using the changes in CD45+EpCAM+ cells in PBMCs as a biomarker for early lung cancer screening." (PMID 36147748, 2022). "Using co-culture of lung cancer cell-derived exosomes with healthy donor peripheral blood mononuclear cells, we recapitulated CD45+EpCAM+ cell formation and increased apoptosis that occurs in patients with primary lung cancer." (PMID 35711455, 2022). "EpCAM (CD326) is an epithelial cell adhesion molecule expressed by the surface of several solid tumors, including prostate-, colorectal- or lung cancer." (PMID 36428811, 2022).
lung carcinoma (continued). "A previous study in lung cancer also observed the association between the increased methylation of H3K9 and epithelial cell adhesion molecule (EpCAM) silencing, the event of which promoted cancer invasion and metastasis." (PMID 36064736, 2022). "Comparative analysis of CEA serum level and CD45+EpCAM+ cell ratio in PBMCs from health volunteers and lung cancer patients." (PMID 36147748, 2022). "How is EpCAM expression in lung cancer switched from upregulation in primary tumor to downregulation in metastatic tumor?" (PMID 36077658, 2022). "In lung cancer, EpCAM has been found to be a downstream target of metastasis-associated protein 1 (MTA1), and MTA1 overexpression can increase EpCAM levels and enhance tumor metastasis, leading to poor prognosis." (PMID 35719973, 2022). "In this study, CD45+EpCAM+ cell ratio in PBMCs of patients with stage I lung cancer was significantly higher than that of patients with tumor stage II and III." (PMID 36147748, 2022). "Further analysis of various serum tumor markers demonstrated that the detection of CD45+EpCAM+ cells in the circulating blood has a higher specificity for the diagnosis of lung cancer than commonly used serological auxiliary tests." (PMID 36147748, 2022). "Further analysis using ROC curves showed that the AUC of CD45+EpCAM+ cell ratio in PBMCs of patients with lung cancer was 0.845, which was slightly higher than that of serum CEA level changes (0.732)." (PMID 36147748, 2022). "We also studied the outcome of lncCDH5-3:3 overexpression in lung cancer cell lines on the expression of EMT-associated proteins, such as E-cadherin and EpCAM." (PMID 35159188, 2022). "We found the presence of CD45+EpCAM+ cells in the tumor tissues of all 38 patients with lung cancer by flow cytometry." (PMID 36147748, 2022). "Further studies will be carried out to dig out the mechanism of metastasis inhibition by EpCAM overexpression in lung cancer cells." (PMID 36077658, 2022). "Taken together, these data suggest that macrophages in tumor microenvironment likely produce TGFβ to repress EpCAM expression in lung cancer cells." (PMID 36077658, 2022). "Then, we asked the question if CD45+EpCAM+ cells also presents in the peripheral blood of these lung cancer patients." (PMID 36147748, 2022). "In this study, flow cytometry was used to detect the presence of CD45+EpCAM+ cells in tumor tissues and peripheral blood mononuclear cells (PBMCs) in patients with lung cancer." (PMID 36147748, 2022). "Previous data showed upregulation of EpCAM in primary lung cancer, leading to a question of EpCAM expression in metastatic lung cancer." (PMID 36077658, 2022). "Taken together, these data suggest that, similar to metastatic lung tumors, EpCAM expression is also repressed in highly metastatic lung cancer cells." (PMID 36077658, 2022). "Then, we want to study if the detection of CD45+EpCAM+ cells in PBMCs is specific for lung cancer patients." (PMID 36147748, 2022). "The sensitivity and specificity of CD45+EpCAM+ cell ratio in PBMCs of lung cancer patients were 81.58% and 88.89%, respectively." (PMID 36147748, 2022). "Analysis of blood samples from metastatic colorectal cancer patients, as well as lung cancer patients, demonstrated that increased EpCAM+EGFR+ events were detected in more than half of the patient samples." (PMID 36613466, 2022). "Further analysis revealed that the AUC of the ratio of CD45+EpCAM+ cells in PBMCs of patients with lung cancer was 0.845, which was slightly higher to that of serum CEA level (0.732)." (PMID 36147748, 2022). "It demonstrates that EpCAM antibodies can increase the targeting of nanoparticles to lung cancer cells." (PMID 36085575, 2022). "Our preliminary data identified an inhibition effect of EpCAM reconstitution on metastasis in lung cancer." (PMID 36077658, 2022).
lung carcinoma (continued). "The AUC of the ratio of CD45+EpCAM+ cells in PBMCs of lung cancer patients was significantly higher than that of ProGRP (0.503), NSE (0.674) serum level, and was not different from serum CYFRA21-1 level (0.801)." (PMID 36147748, 2022). "The pro-metastatic effect of G9a observed in lung cancer is attributed to gene silencing of epithelial cell adhesion molecule (ep-CAM), enhancing invasion." (PMID 33803458, 2021). "The identification of proteins secreted by the A549 CD166 + EpCAM + CSCs subpopulation is important to understand the proteins involved in regulating the niche of CSCs activity in lung cancer." (PMID 33670440, 2021). "In lung cancer, the carcinogenicity of G9a was manifested through the inhibition of the epithelial cell adhesion molecule." (PMID 34336110, 2021). "Regarding CTCs detected using the Veridex CellSearch system, which is based on an anti-EpCAM antibody, the sensitivity for early lung cancer was only 19.3%." (PMID 33547948, 2021). "This suggests that detecting EpCAM+ CTCs and CTECs in post‐therapeutic lung cancer patients is of particular clinical utility, in terms of timely detecting emerging therapeutic resistance and appraising patients’ poor response to combination therapy." (PMID 34455700, 2021). "EpCAM is also highly overexpressed in many human epithelial cancers including colorectal, breast, gastric, prostate, ovarian, and lung cancer." (PMID 33980181, 2021). "Similar to what we found in lung cancer cell lines, we successfully measured EpCAM by RPPA in scaling mixtures of EVs isolated from either HT29 and H1299 or LNCaP and PC3, both showing detectable expression over the background down to 3% of positive EVs." (PMID 34155195, 2021). "Our study is the first attempt toward the utility of a double superficial marker such as CD44+/EPCAM+ for the identification and further the targeting of lung cancer stem cells." (PMID 32391123, 2020). "In summary, our research is an important starting point for further studies that are needed to better define the CD44+/EPCAM+ superficial marker highlighting lung cancer stem cells." (PMID 32391123, 2020). "They used primary lung cancer cells overexpressing EpCAM as selection target and a competitive displacement with EpCAM specific antibody." (PMID 32842557, 2020). "Similar to the CTC (EpCAM+/CK+) sorting in the blood of lung cancer patients develop brain metastases often reported in the literature, GFAP has a greater advantage in the sorting of brain tumor cells in CSF." (PMID 33208163, 2020). "Materials and Methods: This cross-sectional study analyzed the expression of ALDHhigh/low cells and the positivity for CD44 and epithelium cell adhesion molecule (EPCAM) antigens in surgical lung cancer tissues." (PMID 32391123, 2020). "The pan-carcinoma antigen, epithelial cell adhesion molecule (EpCAM), is highly expressed by cancer cells of epithelial origin such as colon, prostate, breast, and lung carcinomas." (PMID 33178203, 2020). "The obtained sequences recognize with high affinity EpCAM+ lung cancer cells and were successfully used to detect CTCs in liquid biopsies." (PMID 32842557, 2020). "As proof of concept of the ALDH enrichment in the population identified by CD44+/EPCAM+ cells, we performed an additional experiment in which primary lung cancer cells were sorted for CD44/EPCAM antigens." (PMID 32391123, 2020). "In the contrary, in ovarian, oral squamous cell carcinoma, colon and lung cancers, expression of EpCAM was correlated with DNA methylation in tissues from cancer patients." (PMID 31225512, 2019). "Based on previous research, several biomarkers have been described in exosomes of lung cancer (compared to normal tissue samples), including several miRNAs and EpCAM from plasma exosomes and LRG1 from urine exosomes." (PMID 30733650, 2019). "Confocal microscopy imaging and spectral profiling of lung cancer tissues confirmed the same protein target for the aptamers and anti-EpCAM antibodies." (PMID 30871104, 2019).
lung carcinoma (continued). "We have recently shown that also lung cancer patients with brain metastases have less CTCs when detected by the EpCAM-dependent CellSearch system." (PMID 31481116, 2019). "A previous study showed that G9a promoted lung cancer invasion and metastasis by silencing the cell adhesion molecule EpCAM, and knockdown of G9a in fast-growing cell lines led to a less aggressive phenotype." (PMID 30348169, 2018). "Another study demonstrated that G9a promoted invasion and metastasis by regulation of the epithelial cellular adhesion molecule (EpCAM) in lung cancer." (PMID 30348169, 2018). "We quantified the size and EpCAM expression of over 2,500 CTCs from 38 patient samples obtained from breast, prostate, lung cancers, and melanoma." (PMID 28883519, 2017). "Epithelial cell adhesion molecule (EpCAM) is expressed at relatively low levels in patients with lung cancer." (PMID 29156821, 2017). "We next isolated primary human EpCAM+ lung cancer cells using a disaggregation protocol to preserve RANK cell surface expression and function, demonstrating a positive correlation between the IHC analysis and RANK flow cytometry (n = 33)." (PMID 29118048, 2017). "EMT-CTCs and EPCAM(+)-CTCs were simultaneously detected prior to operation in cases D1-D3 with lung cancer." (PMID 28423562, 2017). "We have compared the detection of CTCs between the size-based microfluidic chip and the EpCAM-magnetic bead based method in 19 lung cancer patients." (PMID 28039472, 2017). "Increasing amounts of EpCAM also has been correlated with lower life expectancy of lung cancer patients." (PMID 26984381, 2016). "We further performed cell capture assays using the EpCAM+ A549 lung cancer cell line and observed a similarly significant enhancement of cancer cell capture yield by the nanoroughened glass surface." (PMID 27501846, 2016). "To identify the subpopulation of putative CSCs in cancer cell lines, we investigated the expression of three stem cell surface markers (CD166, CD44, and EpCAM) that previously were described as prominent CSCs markers in lung cancer." (PMID 25881239, 2015). "And MTA1 and EpCAM overexpression independently predicted unfavorable prognosis in our 118 lung cancer patients." (PMID 26698569, 2015). "Microfluidic chips coated with EpCAM and microfluidic systems utilizing immunomagnetic principles have been shown to capture CTCs from lung cancer samples with 100% efficiency." (PMID 26484313, 2015). "Taken together, these results indicate that MTA1 signals through EpCAM, at least in part, to stimulate the invasion and migration abilities in lung cancer cells." (PMID 26698569, 2015). "EpCAM is expressed in majority of human epithelial cancers, including breast, colon, gastric, head and neck, prostate, pancreas, ovarian and lung cancer and is one of the most widely investigated protein for its diagnostic and therapeutic potential." (PMID 25695234, 2015). "MTA1 upregulated EpCAM expression in lung cancer cell lines, and EpCAM overexpression rescued the inhibitory effects by silencing MTA1 on cell invasion and migration in vitro." (PMID 26698569, 2015). "The FDA approved CellSearch technology utilizes EpCAM-coated magnetic beads to isolate CTCs in a multitude of cancers in spite of limited detection efficiency (32% in lung cancer)." (PMID 26484313, 2015). "In this study, we demonstrated that over-expression of MTA1 induced EpCAM expression in human lung cancer cell lines, leading to increased cell invasion and migration." (PMID 26698569, 2015). "In this context, overexpression of MTA1 in the three lung cancer cell lines increased EpCAM expression at protein level." (PMID 26698569, 2015). "In summary, our results provided a new insight into MTA1-mediated invasion and migration by enhancing EpCAM level in lung cancer." (PMID 26698569, 2015).